SLAMF1 (signaling lymphocytic activation molecule family member 1)
Diseases named in the same sentence as SLAMF1 in open-access papers (continued):
Sharing a sentence is not in itself a finding about the gene and the disease.
infection (103 papers, 2008 to 2025). The state of being infected such as from the introduction of a foreign agent such as serum, vaccine, antigenic substance or organism. "The receptor Signaling Lymphocyte-Activation Molecule Family 1 (SLAMF1) controls susceptibility to Infection by the lethal Trypanosoma cruzi Y strain." (PMID 32925918, 2020). "We have shown that the receptor Signaling Lymphocyte-Activation Molecule Family 1 (SLAMF1) controls susceptibility to Infection by the lethal T. cruzi Y strain." (PMID 32925918, 2020). "While oxidative stress is a common response to infection, Salmonella survival is reduced in SLAMF1‐deficient mice and can interfere with localization of functional NOX2 in Salmonella‐containing vacuoles (SCVs), linking SLAM proteins and oxidative stress." (PMID 31468702, 2019). "This study subsequently demonstrated that CHO cells expressing SLAMF1 were susceptible to wtMEV infections." (PMID 27657109, 2016). "Taken together, the data clearly demonstrate that infected Slamf1−/− mice have much less T. cruzi amastigotes in their hearts than Slamf1+/+ littermates, which is the most likely cause for the survival of Slamf1−/− mice upon an acute infection by the parasite." (PMID 22807679, 2012). "Rather, the altered local heart response to infection, with much lower T. cruzi amastigotes and altered immune mediators in infected Slamf1−/− mice, are the most likely cause for the survival of Slamf1−/− mice upon an acute infection by the parasite." (PMID 22807679, 2012). "In contrast to myeloid cells, Slamf1−/− and wt cardiomyocytes were equally susceptible to in vitro infection with T. cruzi." (PMID 22807679, 2012). "Since immune cells are primary targets during MeV infection, it is possible that virus-induced SLAMF1-mediated signaling may influence subsequent immune cell interactions and may contribute to the long-term immunosuppression associated with this infection." (PMID 28100610, 2017). "The poor outcome in SLAMF1-deficient mice of experimental infections with Leishmania major, which rely on macrophages for effective clearance, may also be partly explained by impaired migration of macrophage-forming monocytes." (PMID 26834746, 2016). "Moreover, arginase I levels are lower in the heart of Slamf1−/− mice, and we have found that the levels of this enzyme presents in infiltrating myeloid suppressor cells correlate with higher susceptibility to infection." (PMID 22807679, 2012). "SLAMF1 (Signaling Lymphocytic Activation Molecule Family Member 1) encoding CD150, which supports functions of various activated immune cells, such as T helper cells, natural killers, dendritic cells, and macrophages, but also facilitates infection by measles virus, leading to immunosuppression." (PMID 41369330, 2025). "In contrast, HMPV-induced TNF mRNA expression in MDMs was significantly reduced at 3 h post-infection following silencing of either SLAMF1 or TLR4." (PMID 41346628, 2025). "Silencing of SLAMF1 or TLR4 had minimal impact on HMPV-induced IFNB1 mRNA expression, except for a reduction observed in SLAMF1-silenced MDMs at 20 h post-infection." (PMID 41346628, 2025). "The receptor SLAMF1 (CD150) influences infection in a strain-dependent manner by modulating parasite entry and macrophage oxidative responses." (PMID 41568009, 2025). "This means that the neutrophil’s role in the innate immune response against T. cruzi is downregulated in a normal infection, but the depletion of SLAMF1 avoids it." (PMID 39000601, 2024). "SLAMF1 would act during the infection of macrophages controlling parasite replication and therefore affecting survival in mice but in a strain-dependent manner." (PMID 39000601, 2024). "Independently of SLAMF1, with the Y strain infection, there was one common upregulated protein, the radical S-adenosyl methionine domain containing 2 (RSAD2), and with the VFRA strain there was one common downregulated protein, the phospholipase D3 (PLD3)." (PMID 39000601, 2024).
infection (continued). "The qRT-PCR results show that SLAMF1 had different inhibitory effects on PRRSV infection at multiple multiplicities of infection (MOI), among which the MOI of 0.1 and 18 hpi show the most significant effect." (PMID 36552462, 2022). "Signaling lymphocytic activation molecule family member 1 (SLAMF1) is a costimulatory factor that is involved in innate immunity, inflammation, and infection." (PMID 36552462, 2022). "Drastic difference in FeMV replication in vitro between parental Vero cells and Vero cells expressing feline SLAMF1 clearly shows the involvement of SLAMF1 in the infection process." (PMID 35891483, 2022). "More recently, we described increased resistance of Slamf1-/- macrophages to the infection with other parasite strains (Dm28c, M6421, 10R26, and Bug2148) except for one (VFRA)." (PMID 34513737, 2021). "Next, we addressed more in detail the immunopathogenic role of SLAMF1 using in vitro infection of macrophages with 6 genetically diverse parasite strains." (PMID 32925918, 2020). "In order to study the role of SLAMF1 in experimental infections, we selected the two strains, Y and VFRA, that had the most striking different behavior in macrophages regarding to parasite load and their effect on macrophage NOX2 expression and ROS production." (PMID 32925918, 2020). "Parasite load in the intestine of Slamf1-/- mice was significantly lower than in BALB/c mice after infection with the Y strain at EA and LA phases." (PMID 32925918, 2020). "Y and VFRA strains showed a divergent behavior in vitro and the role of SLAMF1 in the in vivo infection was also strikingly different." (PMID 32925918, 2020). "In addition, given that T. cruzi isolated strains present great genetic variability and cause very different infection outcomes, we aimed to investigate whether the host-detrimental role of SLAMF1 observed with the Y strain, can be extended to other T. cruzi strains." (PMID 32925918, 2020). "In agreement with that, 70% of BALB/c mice succumbed to infection with the Y strain, while 100% of Slamf1-/- mice survived." (PMID 32925918, 2020). "Altogether, the role of SLAMF1 in infection is interesting in that it both acts directly as a viral cell surface receptor, and modulates signaling on immune cells key to combating viral and bacterial infections." (PMID 31744090, 2019). "SLAMF1 and nectin-4 are found on separate cells in vivo, immune and epithelial, respectively, contributing to a MeV life cycle that involves infection of both the lymphatic system and various epithelia." (PMID 31366072, 2019). "This suggests that SLAMF1 plays a role in regulating the production of antibodies during infections." (PMID 31744090, 2019). "This is especially true for SLAMF1—the primary entry receptor—since its use is considered vital for establishing infection in the host." (PMID 30232185, 2018). "Herein, we describe a novel internalization pathway for MeV to establish infection that is dependent on its immune receptor, SLAMF1." (PMID 28100610, 2017). "The fluid uptake, filopodium formation, and blebbing observed during MeV infection of SLAMF1-positive cells are dependent on a highly dynamic actin cytoskeleton." (PMID 28100610, 2017). "The subsequent circulation of MeV-infected SLAMF1+ cells in the periphery leads to infection of epithelial tissues in the respiratory tract, which facilitates transmission to new hosts." (PMID 28100610, 2017). "Infection spreads to the local lymph nodes, where a range of SLAMF1-expressing immune cells become infected." (PMID 28100610, 2017). "Combined, these data suggest that MeV particle and fluid uptake occur concurrently after infection and that this process is SLAMF1 dependent." (PMID 28100610, 2017). "SLAMF1 is found on activated B, T, dendritic, and monocyte cells, and is the initial target for infections by measles virus." (PMID 27657109, 2016).
infection (continued). "Subsequently, SLAMF1 and Nectin-4 independent infections of astrocytes were reported using a neurological strain of CDV containing the red fluorescent protein reporter." (PMID 27657109, 2016). "Canine distemper virus prefers to use the canine homologue of SLAMF1, and infections of cells expressing human SLAMF1 (hSLAMF1) are less efficient." (PMID 27657109, 2016). "This stage of infection is critically dependent on the interaction of the virus with the immune cell receptor CD150 or signaling lymphocyte activation molecule (SLAMF1,)." (PMID 27727184, 2016). "Because Slamf1 partakes in bactericidal responses as the receptor and plays a role in protecting against infection with Leishmania major we set out to evaluate how Slamf1-deficient mice would respond to an infection by the intracellular parasite T. cruzi." (PMID 22807679, 2012). "To test this concept we employed an alternative approach, namely administering an anti-Slamf1 monoclonal antibody to infected BALB/c mice once a week during the four weeks post infection with T. cruzi." (PMID 22807679, 2012). "Additionally, HMPV-N mRNA levels were significantly higher in SLAMF1-overexpressing THP-1 cells at 20 h post-infection." (PMID 41346628, 2025). "This agrees with the reduced parasite load in Slamf1-/- macrophages infected by the Y strain, suggesting that SLAMF1 signaling after the T. cruzi interaction affects these critical proteins to resolve the infection." (PMID 39000601, 2024). "Furthermore, in all the VFRA infections, independently of SLAMF1 expression, we had an upregulation of the IL-11 pathway." (PMID 39000601, 2024). "Also, in the VFRA infections, independently on SLAMF1, GSL catabolism was detected, which would be a specific molecular process decreased only by this strain." (PMID 39000601, 2024). "Therefore, we studied the role of SLAMF1 by quantitative proteomics in a macrophage in vitro infection and the different responses between Y and VFRA strains of Trypanosoma cruzi." (PMID 39000601, 2024). "Furthermore, in all the VFRA infections, independently of SLAMF1 expression, there was a downregulation of phosphatidylglycerol (PG) biosynthesis." (PMID 39000601, 2024). "SLAMF1 is a costimulatory factor that is involved in innate immunity, inflammation, and infection." (PMID 36552462, 2022). "The results show that interfering with the SLAMF1 gene could effectively inhibit the proliferation of the PRRSV for 36h after infection." (PMID 36552462, 2022). "In the context of T. cruzi infection, SLAMF1 controls the susceptibility of infection by the virulent Y strain, since Slamf1−/− mice, lacking the SLAMF1 receptor, are resistant to a lethal T. cruzi Y strain challenge." (PMID 34976301, 2021). "H interaction with SLAMF1 or other cellular receptors induces a conformational change in F that leads to fusion of the viral envelope with the plasma membrane and initiation of infection with delivery of the genome into the cell cytoplasm." (PMID 32891958, 2021). "CHO or Vero cells expressing SLAMF1 became susceptible to infections with wtMeV and used this receptor without the need to adapt and use CD46." (PMID 27657109, 2016). "Pools each containing 450 different clones were further subdivided until it was determined that an individual expression plasmid containing the coding sequence for SLAMF1 could promote wtMeV infections." (PMID 27657109, 2016). "The reasons for this apparent discrepancy may lie in the fact that Slamf1 affects a different and earlier process in the infection of macrophages by T. cruzi than L. major, as the two parasites invade the cells by different mechanisms." (PMID 22807679, 2012). "Also, upon SLAMF1 depletion, we observed reduced HMPV-N mRNA and protein levels at late time points of infection, which could suggest that SLAMF1 affects viral uptake or replication that could lead to altered IFNB1 expression." (PMID 41346628, 2025).
infection (continued). "In addition, Slamf1-/- macrophages became more resistant to the infection with the same strain." (PMID 34513737, 2021). "As well as delivering MeV to sites for onward transmission, infection of SLAMF1+ lymphocytes and monocytes also contributes to the prolonged immunosuppression reported for infected subjects and may explain their increased susceptibility to secondary bacterial infections." (PMID 28100610, 2017). "Importantly, MeV spread within the lymphatic system, in the early stages of disease, is SLAMF1 dependent, and this entry pathway may contribute to the widespread infection seen in lymph nodes." (PMID 28100610, 2017). "A larger overlap in DEGs was noted between the two time points in the infection group with 74 DEGs that enriched to processes involved in wound repair (HBEGF and MT2A) as well as immune responses to pathogens (CCL20, IL6, and SLAMF1)." (PMID 40576342, 2025). "Our meta-analyses indicated that five out of the eight significantly identified genes (CD40, ICOS-L, SLAMF1, CD84, IL-21R) were downregulated continuously during infection." (PMID 37146079, 2023). "After initiation of infection in the respiratory tract, MeV is transported to the draining lymph node (LN) where it infects CD150/SLAMF1-expressing cells." (PMID 32891958, 2021). "We found that at 1 and 6 hpi all parasite strains grouped according to the time post-infection in BALB/c and Slamf1-/- macrophages, but principal changes were found in BALB/c at 24 hpi." (PMID 32925918, 2020). "Given the complex bitropic life cycle of morbilliviruses in SLAMF1-positive immune cells and nectin-4 positive epithelia, the role of restriction factors, including BST2, in the innate response to infection is an area of increasing interest." (PMID 31366072, 2019). "Interestingly, lower levels of arginase I mRNAs were also observed in Slamf1−/− mice especially at the peak of parasite load 21 dpi, consistent with our previous finding that sustained arginase I expression through the acute infection is detrimental for the host." (PMID 22807679, 2012). "However, as circulating parasite levels are similar in Slamf1−/− mice and the in vitro susceptibility of cardiomyocytes to infection is not altered by Slamf1 deficiency, is likely that T. cruzi blood trypomastigotes are unable to penetrate the heart directly to infect the cardiomyocytes." (PMID 22807679, 2012). "Here, silencing TLR4 or SLAMF1 in MDMs reduced HMPV-induced p38 MAPK activation at early time points, indicating that HMPV triggers signaling downstream of both receptors early during infection in MDMs." (PMID 41346628, 2025). "Collectively, these results indicate that both TLR4 and SLAMF1 are required for the early induction of TNF mRNA by HMPV in human MDMs, while only SLAMF1 contributes to HMPV-mediated IFNB1 expression at later stages of infection." (PMID 41346628, 2025). "Regarding the Y strain infections, independently of the presence/absence of SLAMF1, there are five GO terms shared, like the positive regulation of TLR7 and TLR9 signaling pathways and the alpha–beta T cell activation." (PMID 39000601, 2024). "Considering the strain-specific proteins without a dependency on SLAMF1, Y strain infections displayed one common upregulated protein (RSAD2), and VFRA strain infections had one common downregulated protein (PLD3)." (PMID 39000601, 2024). "Is in the intestine where we can find increased expression NOX2 in the absence of SLAMF1 as it does in macrophages in vitro after infection with the Y strain." (PMID 32925918, 2020). "Here we found a detrimental increase in Cd4 / Il6 / Il10 expression in heart tissue of BALB/c mice infected with the Y strain, not observed in the absence of SLAMF1, in which Cd8 was increased at the LA phase likely allowing a better control of the infection." (PMID 32925918, 2020). "Notably, infection with VFRA resulted in detectable, but very low parasite load, both in BALB/c and Slamf1-/- intestines." (PMID 32925918, 2020).
infection (continued). "Infection was shown to be due to wtMeV’s ability to use the cotton rat SLAMF1 as a receptor, unlike the mouse homologue." (PMID 27657109, 2016). "Again, these adenocarcinoma cell lines did not express SLAMF1 nor were wtMeV infections blocked by antibodies against MCP/CD46 or SLAMF1." (PMID 27657109, 2016). "It has been shown that B cells lacking Slamf1 cannot form the lasting interactions with Tfh cells that are required for GC formation, and yet Oct2 mice do form GC upon infection and immunization." (PMID 24688485, 2014). "Thus, to further characterize the role of SLAMF1, we performed a quantitative proteomic analysis to uncover the differences between BALB/c and Slamf1-/- macrophages in the in vitro infection by T. cruzi, identifying the different and common responses between Y and VFRA strains of this parasite." (PMID 39000601, 2024). "In contrast, infection with VFRA strains neither caused mortality in BALB/c, nor in Slamf1-/- mice." (PMID 32925918, 2020). "Similarly, infection of epithelial cells by CDV using Nectin-4 is required for clinical disease and release of the virus, but not for immune suppression, which is mediated by interaction with SLAMF1." (PMID 27657109, 2016). "During infection of BALB/c mice with T. cruzi splenic cellularity increased approximately 8-fold By contrast, this expansion was only 3-fold in the spleens from Slamf1−/− mice indicative of a much lesser activation state at early times although at day 21 d.p.i. cellularity increases were similar." (PMID 22807679, 2012). "Interestingly, unlike wt mice, Slamf1−/− mice did not die from the infection and eventually recovered." (PMID 22807679, 2012). "Not surprisingly, because cardiomyocytes do not express Slamf1, upon infection with T. cruzi these cells, whether isolated from wt or Slamf1−/− BALB/c mice, produced equal amounts of IFNγ and nitric oxide (NO) upon in vitro infection." (PMID 22807679, 2012). "However, SLAMF1 was not required in infections with a Gram+ bacteria like Staphylococcus aureus." (PMID 34513737, 2021). "Tnf gene expression increased with infection, but in the absence of SLAMF1, higher levels of Tnf expression were observed at 1 and 6 hpi, decreasing at 24 hpi, suggesting that SLAMF1 might be retarding the induction of Tnf in infected macrophages with all the strains tested." (PMID 32925918, 2020). "Given the timing of the surface expression of SLAMF1 and SLAMF8 and their opposite effect on phagocyte activation, we hypothesize that these two SLAMF molecules represent a rheostat mechanism that modulates the extent of inflammation at different stages of an infection." (PMID 26834746, 2016). "Taken together, the data indicate that the difference in susceptibility of Slamf1−/− and wt BALB/c mice could not be attributed to selective differences in the alterations of major leukocyte subpopulations in those organs affected by the infection." (PMID 22807679, 2012). "Besides, in the absence of Slamf1, macrophages and DCs produce less myeloid cell specific factors that are key in influencing the host response to parasite and eventually the outcome of the infection." (PMID 22807679, 2012). "We detected some significantly upregulated proteins upon infection: IRG1, GBP5, ICAM1, ACSL1, and PDL1 independently on the presence or absence of SLAMF1." (PMID 39000601, 2024). "Thus, we performed a proteomic study on the effect of the absence of SLAMF1 in macrophages after Y and VFRA strains of in vitro infection." (PMID 39000601, 2024). "Additionally, SLAM receptors (such as SLAMF1, SLAMF6, and SLAMF8) have also been shown to modulate innate immune responses following infection with both gram-negative and positive bacteria." (PMID 31744090, 2019).
infection (continued). "Knockdown of TLR4 or SLAMF1 did not substantially alter HMPV-induced STAT1 phosphorylation at early time points, although SLAMF1 depletion significantly reduced STAT1 phosphorylation at 20 h post-infection, consistent with the reduced HMPV-N mRNA and protein levels in these MDMs." (PMID 41346628, 2025).